UBXN6 (UBX domain protein 6)
Description:
May negatively regulate the ATPase activity of VCP, an ATP-driven segregase that associates with different cofactors to control a wide variety of cellular processes. As a cofactor of VCP, it may play a role in the transport of CAV1 to lysosomes for degradation. It may also play a role in endoplasmic reticulum-associated degradation (ERAD) of misfolded proteins. Together with VCP and other cofactors, it may play a role in macroautophagy, regulating for instance the clearance of damaged lysosomes.
Synonyms: UBXD1; UBXDC2
Tractability: Small molecule: a structure with a bound ligand is known. Antibody: UniProt places it where antibodies can reach, with high confidence. PROTAC: ubiquitination databases record sites on it; its protein half-life has been measured.
Gene: Protein-coding gene on chromosome 19 (4,444,999 to 4,457,794, reverse strand). Ensembl gene ENSG00000167671.
Subcellular location: Cytoplasm; Cytoplasm, cytosol; Membrane; Nucleus; Cytoplasm, cytoskeleton, microtubule organizing center, centrosome; Early endosome membrane; Late endosome membrane; Lysosome membrane
Subcellular location (Human Protein Atlas): Cytosol; Golgi apparatus
Gene Ontology:
Molecular function: ATPase binding; protein binding
Biological process: endosome to lysosome transport via multivesicular body sorting pathway; ERAD pathway; macroautophagy; mitophagy; protein unfolding; response to stress
Cellular component: ATPase complex; cytoplasm; cytosol; early endosome membrane; endosome; extracellular exosome; late endosome membrane; lysosomal membrane; membrane; nucleus; protein-containing complex; centrosome
Genetic constraint (gnomAD): Loss-of-function variants: 46 observed, 50.38 expected, observed/expected ratio (o/e) 0.91, 90% interval 0.72 to 1.17. The synonymous counts are far from expectation, so gnomAD's model fits this gene poorly and the ratio says little. Missense variants: 672 observed, 579.48 expected, observed/expected ratio (o/e) 1.16, 90% interval 1.09 to 1.24. Synonymous variants: 316 observed, 255.82 expected, observed/expected ratio (o/e) 1.24, 90% interval 1.13 to 1.36.
Homologues: Orthologues: chimpanzee UBXN6 (99% identical), macaque UBXN6 (95% identical), pig UBXN6 (88% identical), dog UBXN6 (86% identical), guinea pig UBXN6 (81% identical), mouse Ubxn6 (81% identical), rat Ubxn6 (80% identical), zebrafish ubxn6 (54% identical), tropical clawed frog ubxn6 (51% identical), Drosophila melanogaster Gint3 (34% identical), Caenorhabditis elegans ubxn-6 (31% identical). Paralogues in human: ASPSCR1 (20% identical).
Diseases named in the same sentence as UBXN6 in open-access papers:
UBXN6 is named in the same sentence as 12 diseases in open-access papers, as found by Europe PMC text mining. Sharing a sentence is not in itself a finding about the gene and the disease. The quoted sentences say what the papers report.
autoimmune disease (1 paper, 2024). A disorder resulting from loss of function or tissue destruction of an organ or multiple organs, arising from humoral or cellular immune responses of the individual to their own tissue constituents. "Next, we explored whether UBXN6 deficiency modulated the activation of the NLRP3 inflammasome, which is critical for the innate defense of patients with autoinflammatory and autoimmune diseases." (PMID 39438692, 2024).
osteosarcoma (1 paper, 2014). A usually aggressive malignant bone-forming mesenchymal neoplasm, predominantly affecting adolescents and young adults. "In humans, UBXN6 is reported to play a role in diverse scenarios: for example, it was shown to play a role in Caveolin turnover in human osteosarcoma U2OS cells." (PMID 25369031, 2014).
Sepsis (1 paper, 2024). Sepsis is defined as life-threatening organ dysfunction caused by a dysregulated host response to infection. "In sepsis patients, UBXN6 levels were negatively correlated with inflammatory gene profiles but positively correlated with the levels of Forkhead box O3 (FOXO3) and several autophagy/mitophagy-related genes." (PMID 39438692, 2024). "Together, these data reveal that UBXN6 serves as an activator of autophagy and regulates inflammation to maintain immune system suppression during human sepsis." (PMID 39438692, 2024). "Our data also highlight the clinical relevance of UBXN6 in terms of human sepsis, particularly in the context of immunosuppression." (PMID 39438692, 2024). "In this study, we report that UBXN6 is upregulated in humans with sepsis and may serve as a pivotal regulator of inflammatory responses via the activation of autophagy." (PMID 39438692, 2024). "An analysis of data from publicly available sepsis cohorts further revealed that, compared with HCs, sepsis patients in both cohorts presented significantly increased expression of UBXN6, which was inversely correlated with the expression levels of inflammatory genes." (PMID 39438692, 2024). "In addition, our findings underscore the importance of the role of UBXN6 in terms of immunosuppression during sepsis, suggesting the potential efficacy of novel therapeutics targeting UBXN6 in patients with systemic inflammation." (PMID 39438692, 2024). "To further assess the in vivo role of UBXN6 in the context of immunosuppression, a significant immunological feature of severe sepsis, we established a murine model of immunosuppression via a two-hit approach involving cecal ligation and puncture (CLP) and secondary bacterial infection." (PMID 39438692, 2024). "Notably, the upregulation of UBXN6 in sepsis patients was negatively correlated with inflammatory gene profiles but positively correlated with the expression of Forkhead box O3, an autophagy-driving transcription factor." (PMID 39438692, 2024).
cancer (1 paper, 2024). A tumor composed of atypical neoplastic, often pleomorphic cells that invade other tissues. "Cancer cells exhibit moderate cytoplasmic and/or nuclear immunoreactivity in the UBXN6 protein." (PMID 38365777, 2024).
UBXN6 also shares sentences with these, for which no sentence is quoted: amyotrophic lateral sclerosis (1 paper); bacterial infection (1); Dystonia (1); gastric cancer (1); infection (1); myopathy (1); neurodegenerative disease (1); renal clear cell carcinoma (1).